CRP (C-reactive protein)
Diseases named in the same sentence as CRP in open-access papers (continued):
Sharing a sentence is not in itself a finding about the gene and the disease.
heart disease (continued). "For example serum C-reactive protein levels have been shown to be useful in risk models for heart disease but they are also altered in people with an array of autoimmune or infectious disorders." (PMID 25568804, 2014). "The association of NLR and CRP has been already described for patients with cardiac disease and for patients with oncologic surgery in the literature." (PMID 23457609, 2013). "Obese children also have a high risk of development of early heart diseases since 13-25% of them showed high levels of C-reactive protein, 40-50% had increased triglycerides (blood fat) levels and 30-70% had low HDL (good cholesterol) levels." (PMID 20442827, 2009). "Generally, CRP > 3.0 mg/L is a major risk factor for heart disease." (PMID 41342048, 2025). "The hs-CRP is a reliable inflammatory biomarker and prognostic marker for cardiovascular events, and a meta-analysis of 54 prospective studies involving more than 160,000 individuals showed that elevated CRP concentrations increase the risk of heart disease and cardiovascular mortality." (PMID 39599729, 2024). "In addition, compared with general and severe patients, critical patients were more likely to have underlying cardiac disease, lower levels of lymphocyte counts, higher levels of C-reactive protein and procalcitonin." (PMID 33634177, 2021). "The deficiency/marginal deficiency group had significantly higher mean Hs CRP measurements, proportion using antihypertensive medication, and a history of heart disease, and significantly lower HbA1c, T‐Cho, LDL‐C, TG, TP, Alb, and eGFR measurements, and proportion of non–daily drinkers." (PMID 33304719, 2020). "It is evident that there are marked increases in CRP and oxidative stress levels in obese children with MetS, and these could pose a risk for heart diseases." (PMID 25241610, 2014). "Dietary GI and GL were progressively associated with CHD in various populations and with plasma CRP levels, in general and in healthy middle-aged women, suggesting an explanatory link between women's ischaemic heart disease with overweight and their susceptibility to insulin resistance." (PMID 23311512, 2013). "We hypothesized that increased levels of fine PM would be associated with intra-individual increases in CRP levels in those with heart disease." (PMID 17270049, 2007). "The cardiac sub-study will investigate whether any beneficial effect of bisoprolol is limited to those people with COPD with unrecognised heart disease as determined by risk stratification based on echocardiography and blood concentrations of Galectin, hs-cTnI, hs-CRP and NTproBNP." (PMID 35422024, 2022). "Moreover, elevated levels of serum CRP can be associated with heart disease." (PMID 34711013, 2021). "As shown in the intersection plot, the majority of CpGs detected in earlier EWAS overlapped with the cluster 5 (HR-InsRes) -specific CpG sites, especially those found in common for CRP, T2D and heart diseases." (PMID 41547928, 2026). "XGBoost identified heart diseases (37.25 %), creatine kinase (11.76 %) and C-reactive protein (10.46 %) as the most relevant predictors." (PMID 40438551, 2025). "Comparative analysis of the importance of each variable unveiled that age, C-reactive protein, heart diseases and the three SNPs (rs10490770, rs10774671 and rs77534576) were relevant in all models, except for SVM and KNN, although with varying importance." (PMID 40438551, 2025). "XGBoost detected the presence of heart diseases as the factor with the strongest predictive value (37.25 %), followed by elevated levels of creatine kinase (11.76 %) and C-reactive protein (10.46 %)." (PMID 40438551, 2025). "Elevated inflammatory markers like CRP and IL-6 highlight the inflammatory bridge between poor OH and heart disease." (PMID 40722588, 2025).
heart disease (continued). "Specifically, we assessed the utility of the CALLY index, a score based on straightforward biochemical markers—CRP, serum albumin, and lymphocytes—which has previously demonstrated prognostic value in non-cardiac diseases." (PMID 39767174, 2024). "On the other hand, circulating sST2 levels increase in response to inflammatory diseases and heart diseases, and correlations between sST2 and inflammatory and cardiac biomarkers (CRP, NT-proBNP) were found to be significant." (PMID 39457043, 2024). "CRP is well recognized as a marker of acute infection and has also been used as a marker and prognostic indicator of heart disease." (PMID 37484982, 2023). "The mortality score COVEG was also created and defined by age ≥ 54, neutrophil–lymphocyte ratio ≥ 2.88, D-dimer ≥ 0.795, C-reactive protein ≥ 30.1, serum ferritin ≥ 406, and the presence of cardiac diseases." (PMID 36750802, 2023). "In contrast, patients with an eGFR ≥ 60 ml/min/1.73 m2 and higher vitamin D concentrations had a 2.8% reduced mortality risk (HR = 0.972; CI = 0.95-0.99; p = 0.0097) even after adjusting for potential confounders such as sex, heart disease, and CRP value." (PMID 37727794, 2023). "C-reactive protein is the most commonly used acute phase reactant in the diagnosis and prognosis of heart disease." (PMID 37484982, 2023). "For decades, it has been demonstrated that CRP is elevated in patients with HF, a heart disease that induces a systemic inflammatory response." (PMID 36185864, 2022). "The results presented here show a gradual increase in IL-1β and CRP levels even in the ω-3G, confirming the presence of an inflammatory effect induced by heart disease and CHF as reported by previous studies." (PMID 34265016, 2021). "C-reactive protein (CRP) has long been used as a marker of systemic inflammation, where the level of CRP increases several hundred fold within hours of an inflammatory occurrence and it is found to be over-expressed in heart disease." (PMID 32599804, 2020). "Similar to our results, significantly higher serum CRP concentration was found in dogs with decompensated CHF compared with compensated dogs with heart disease and healthy dogs." (PMID 33167963, 2020). "While most research is on European or European-American CRP samples, a 2014 review study found that CRP was a strong independent predictor of inflammation and heart disease across different ethnic groups." (PMID 33141863, 2020). "In the Kuopio Ischaemic Heart Disease Risk Factor Study, serum total n-6 PUFA and linoleic acid, the predominant n-6 PUFAs, were associated with lower C-reactive protein (CRP) values." (PMID 30866565, 2019). "Five studies 38 (n=4669), one of which was conducted in children aged 16 years old33 and two in participants with comorbid heart disease, reported significantly higher CRP levels in participants with a diagnosis of GAD." (PMID 31326932, 2019). "The wild genotypes of the IL6 and IL8 gene polymorphisms were present at a high frequency and with elevated CRP expression and proved to be good predictors of heart disease." (PMID 30804931, 2019). "Increased concentrations of CRP have been demonstrated in acquired and congenital cardiac diseases in dogs." (PMID 29573742, 2018). "A few studies demonstrated increased concentrations of C-reactive protein (CRP), a major acute-phase protein, in cardiac diseases in dogs." (PMID 29573742, 2018). "Growth differentiation factor-15 (GDF-15), Cystatin C and C-reactive protein (CRP) have been discussed as biomarkers for prediction of cardiac diseases." (PMID 29771963, 2018). "Two common blood tests for heart disease are a cholesterol test and a C-reactive protein (CRP) test." (PMID 28894472, 2017). "Many studies have suggested that the role of CRP in cardiac disease is as an acute phase-reactant protein." (PMID 24885051, 2014).
heart disease (continued). "While CRP levels are higher in females compared with males, males develop heart disease more frequently and have a higher positive correlation with CRP compared with females." (PMID 24944619, 2014). "Presence of psychiatric disorder at baseline was related to age or family history of heart disease, as well as higher CRP levels." (PMID 25007072, 2014). "As an example of probable confounding, it has been shown that C-Reactive Protein (CRP) levels change with changing levels of other markers of inflammation and with levels of exposure to environmental risk factors for heart disease." (PMID 16859537, 2006). "Research has shown that individuals with higher hs-CRP levels are at an increased risk of heart disease, independent of other traditional risk factors." (PMID 39273041, 2024). "C-reactive protein (CRP) is an important biomarker used for the early detection of cardiac diseases and is sensitive to systemic inflammation (SI) secreted into the blood stream by liver cells, thus rapidly increasing inflammation by several orders of magnitude." (PMID 37185491, 2023). "CRP has been shown to promote atherogenesis making it deleterious in heart diseases." (PMID 37484982, 2023). "Our highly powered analysis and other MR studies show that CRP is unlikely to play a credible causal role in the risk of certain types of heart diseases." (PMID 37298077, 2023). "The most important predictor variables were age, ASA, cardiac disease, and CRP value." (PMID 35169871, 2022). "In addition to the side effects, other outcomes will be evaluated, including circulating C-reactive protein (CRP) concentration, circulating markers of inflammation, oxidative stress and cardiac disease and nutritional and metabolic markers." (PMID 34501251, 2021). "The high-sensitivity (hs) CRP test, which is often used to check for risk of heart disease, was not used in these two trials." (PMID 32325778, 2020). "Therefore, a study of CRP levels in saliva and prediction of heart disease onset is a good example of the relationship between gene activity and diseases." (PMID 32019214, 2020). "In conclusion, our network meta-analysis showed that long-term using statins reduced inflammatory factors including CRP and IL-6, increased lung function index including FEV1% and FEV1/FVC%, and reduced the risk of AECOPD, heart disease-related mortality and all-cause mortality." (PMID 30674312, 2019). "Current evidence suggests that inflammation and biomarkers, including high-sensitivity CRP, may be as important as cholesterol in determining the development of atherosclerosis and heart disease." (PMID 24944619, 2014). "It’s also becoming clear that high levels of CRP may point to the presence of inflammation in blood vessels and be an early marker for heart disease." (PMID 24353529, 2013). "Interestingly, the individuals with cardiac disease have a median value of CRP [0.20 mg/l] that was within the lowest quintile of CRP distribution in apparently healthy elderly participants in other studies." (PMID 17270049, 2007). "Previous studies have demonstrated that the CALLY index, calculated using C-reactive protein (CRP), albumin, and lymphocytes, is a reliable indicator of mortality in patients with non-cardiac diseases." (PMID 39767174, 2024). "The ESR-to-CRP ratio has recently been involved in the diagnosis of cardiac diseases; nevertheless, no significant alteration was noticed in the current study." (PMID 40863337, 2025). "Another important parameter is CRP (C-reactive protein), with elevated levels (≥5 mg/L) being indicative of a poor prognosis in cardiac disease, regardless of other hemodynamic parameters or even BNP levels." (PMID 41369404, 2025).
heart disease (continued). "Age, oxygen saturation upon admission, heart disease, leukocyte levels, lymphocytes, LDH, SGPT, SGOT, BUN, creatinine, C-reactive protein, ferritin, and PaO2/FiO2 showed a relationship with mortality within 60 days in the bivariate analyses, and these factors were included in the multivariate model." (PMID 35766661, 2022). "There were no sex differences in terms of age, HADS-D, heart disease severity and the two interrelated parameters BMI and hs-CRP (r = 0.305)." (PMID 35370818, 2022). "With this programmable platform, the initial application of chip-based multianalyte detection systems for cardiac applications was completed by targeting two inflammatory biomarkers, C-reactive protein (CRP) and interleukin-6 (IL-6), both relevant to the cardiac disease cascade." (PMID 30995728, 2019). "Results showed lower education predicted higher CRP levels independent of income in a sample of patients with heart disease." (PMID 27301295, 2016). "ESR and CRP are, also, suggested annually as a nonspecific workup that could indicate cardiac disease." (PMID 40658121, 2025). "Currently, heart disease diagnosis is mainly based on non-imaging biomarkers, such as cardiac troponin, both I and T forms, C-reactive protein and high-sensitivity C-reactive protein, creatine kinase, natriuretic brain peptide (BNP), and NT- pro BNP, in addition to coronary angiography." (PMID 40565029, 2025). "Lastly, although we hypothesized that inflammatory changes caused by canine heart disease may increase the serum concentration of ESM-1, serum levels of CRP were not measured in every dogs and not correlated with serum ESM-1, remaining as a limiting point." (PMID 35790968, 2022). "Notably, they had significantly higher levels of SpO2 and platelet counts, and lower levels of CK-MB, Hs-CRP, and IL-8 on admission compared with those dying without cardiac disease, which was of opposite trends in that among the survivors." (PMID 33553255, 2020). "They assumed that the relationship between depressive symptoms and cardiac diseases might be mediated by BMI but not CRP levels." (PMID 28061774, 2017). "Moreover, they had lower levels of lymphocyte count, albumin, EGFR, and TBIL, and higher levels of SBP, cardiac biomarkers (Hs-TnI, CK-MB, Myo, and NT-proBNP), WBC, neutrophil, inflammatory factors (Hs-CRP, IL-2R, IL-6, IL-8, and TNFα) and D-dimer in comparison to survivors without cardiac disease." (PMID 33553255, 2020). "In defining the importance of a predictor both in terms of the absolute value and the percentage of times a non-zero estimate was seen, cardiac disease, CXR and CRP, SpO2, WBC, and eGFR were deemed important predictors of death or intubation within 7 days of hospital admission." (PMID 36105420, 2022).
kidney disease (224 papers, 2005 to 2026). "Hemodialyzed patients frequently present with elevated baseline levels of inflammatory markers due to their underlying renal disease and the dialysis procedure itself, thereby leading to an augmented CRP response." (PMID 38255209, 2024). "The IFLS study in Asian populations showed that the elevated level of high‐sensitivity c‐reactive protein (hs‐CRP) is significantly associated with the risk of diabetes, heart disease, hypertension, and kidney disease." (PMID 37102663, 2023). "Chronic inflammation is an essential CV risk factor in patients with kidney disease and is characterized by the enhanced production of CRP and other inflammatory mediators, including IL-6 and IL-8." (PMID 35453489, 2022). "The adherence of monocytes is also modified by CRP and the type of kidney disease (underlying disease)." (PMID 34580787, 2021). "IL-6-associated and CRP-associated metabolites including pseudouridine, l-phenylalanine, and p-hydroxyphenylacetic acid were reported to be associated with renal disease, which were seen obviously abundant in the serum instead of GCF in the ESRD patients." (PMID 33903806, 2021). "The mediation analysis was performed testing several variables known to be linked to kidney disease, including C-reactive protein, IL-6, uric acid, azotemia, triglycerides, ApoA1, ApoB, and HbA1c, and that resulted associated with mitokines, (data not shown)." (PMID 33131010, 2021). "Increased serum levels of CRP in SLE patients are correlated with renal disease activity and increased risk for LN development." (PMID 33644084, 2020). "Once adjusted for all parameters, being male, having a higher baseline serum sodium and CRP as well as a previous diagnosis of Renal disease were all still significantly associated with AKI but RAAS inhibition was not." (PMID 33141867, 2020). "The relation between OTA plasma levels and specific disease risk markers, such as body mass index, kidney disease and inflammation (C-reactive protein), was investigated." (PMID 32121036, 2020). "Anti-CRP antibody levels have previously been found to correlate with disease activity, but the present study is the first to show an association with renal disease activity assessed with the BILAG index." (PMID 20003354, 2009). "Furthermore, one potential mechanism of the association between DII and kidney diseases is that a pro-inflammatory diet can induce chronic inflammation, leading to the upregulation of various pro-inflammatory factors, such as CRP." (PMID 38386646, 2024). "CRP is a marker of inflammation, and elevated serum levels are associated with an increased risk of cardiovascular events and mortality in the general population as well as in patients with kidney disease." (PMID 37790129, 2023). "There were significant association between sex and renal disease with CRP." (PMID 37626700, 2023). "Lower SI was associated with increased CRP in patients with severe renal disease." (PMID 36138920, 2022). "Kidney disease is considered an inflammatory state, based on elevated levels of C-reactive protein and inflammatory cytokines." (PMID 40309771, 2025). "The phase-2 RESCUE trial initially supported the ziltivekimab's efficacy in reducing inflammatory biomarkers, including CRP, among patients with moderate to severe kidney disease and elevated hs-CRP levels at baseline." (PMID 39404934, 2024). "This modest correlation between hs-CRP and FLCs observed in this population of patients was similar to the correlation between CRP and FLCs reported by other groups in patients with inflammatory diseases such as kidney disease." (PMID 38725572, 2024). "Similar data have been assessed in more than two thousand non-dialyzed patients with CKD in whom LVMI and ratio of high-density lipoprotein and C-reactive protein were independently correlated with renal disease progression." (PMID 38256388, 2024).